TUSC2 (tumor suppressor 2, mitochondrial calcium regulator)
Diseases named in the same sentence as TUSC2 in open-access papers (continued):
Sharing a sentence is not in itself a finding about the gene and the disease.
thyroid cancer (10 papers, 2016 to 2025). "Taken together, these novel findings demonstrate that TUSC2 is negatively associated with thyroid cancer aggressiveness and thus this tumour suppressor could represent a novel potential target and biomarker for thyroid cancer therapy." (PMID 31973107, 2020). "Since many studies have described a significant impact of the loss or reduction of the TUSC2 tumour suppressor on different cancer types, the aim of this study was to deepen the knowledge on the molecular mechanisms modulated by this tumour suppressor gene in thyroid cancer cells." (PMID 31973107, 2020). "A recent study reported TUSC2’s tumor-suppressing activity in thyroid cancer via SMAC/DIABLO and CYTOCHROME C protein." (PMID 40243558, 2025). "This assumption is further corroborated by the reported ability of the Twist1/miR-584/TUSC2 pathway to induce a resistance to apoptosis of thyroid cancer cells." (PMID 34575184, 2021). "The obtained results clearly indicate that TUSC2 restoration decreased the migration and invasion of thyroid cancer cell lines." (PMID 31973107, 2020). "Overall, these results suggest that SMAC/DIABLO is a mediator of TUSC2 biological effects in thyroid cancer cells." (PMID 31973107, 2020). "The aim of this study was to gain insight into the molecular mechanisms induced by TUSC2 in thyroid cancer cells." (PMID 31973107, 2020). "Nevertheless, the exact biological function of TUSC2 in thyroid cancer cell lines remains unexplored." (PMID 31973107, 2020). "Here, we report that TUSC2 restoration inhibits tumour cell growth by arresting the cell cycle progression and by reducing the motility phenotype of thyroid cancer cell lines." (PMID 31973107, 2020). "The Twist1/miR-584/TUSC2 pathway plays a role in the resistance to apoptosis in thyroid cancer cells." (PMID 33381597, 2020). "To further gain insight into the molecular mechanisms induced by TUSC2 in thyroid cancer cells, we focused on the role of SMAC/DIABLO." (PMID 31973107, 2020). "In conclusion, our study identified a novel TWIST1/miR-584/TUSC2 pathway that plays a role in resistance to apoptosis of thyroid cancer cells." (PMID 27661106, 2016). "Additionally, TUSC2 was found to induce thyroid cancer cell apoptosis via intrinsic apoptosis factors SMAC/DIABLO and cytochrome C upregulation." (PMID 37173921, 2023). "However, inhibition of miR-584 restored TUSC2 expression and led to enhanced thyroid cancer cell apoptosis." (PMID 37173921, 2023). "Thyroid cancer cell lines overexpressing TUSC2 demonstrate a significant increase in SMAC/DIABLO and cytochrome C expression following treatment with an apoptosis inducer, suggesting that TUSC2 sensitizes thyroid cancer cells to apoptosis via upregulation of SMAC/DIABLO and cytochrome C." (PMID 37173921, 2023). "Likewise, in thyroid cancer, we have reported that the overexpression of miR-584 induces a reduction in TUSC2 by directly targeting its 3′untranslated region." (PMID 31973107, 2020). "Notably, our findings indicate the possibility that restoration of TUSC2 expression, combined with specific pro-apoptotic stimuli, could represent a cancer strategy for patients affected by aggressive forms of thyroid carcinoma." (PMID 31973107, 2020). "Thus, our data highlight a tumour suppressor role of TUSC2 in thyroid carcinogenesis, suggesting that it could be a promising target and biomarker for thyroid carcinoma." (PMID 31973107, 2020). "This decrease in TUSC2 expression is mediated by miR-584, which is significantly upregulated by the transcription factor TWIST, in thyroid cancer, discovered by Orlandella and colleagues." (PMID 37173921, 2023). "Additionally, in thyroid cancer cell lines, overexpression of FUS1/TUSC2 increased levels of Smac/Diablo that blocks caspase regulatory inhibitors of apoptosis proteins and cytochrome c." (PMID 35181743, 2022).
thyroid cancer (continued). "We have previously reported, by quantitative real-time PCR (q-RT-PCR) and immunohistochemistry analysis, that TUSC2 is downregulated in almost all ATC samples and in the vast majority of PTC samples, suggesting an important role of this tumour suppressor in thyroid cancer progression." (PMID 31973107, 2020). "We have previously reported that TUSC2 rescues the resistance to apoptosis induced by its negative regulator, miR-584, in thyroid cancer cells." (PMID 31973107, 2020). "Here, we stably transfected TUSC2 in papillary (TPC-1) and in anaplastic (8505C) thyroid cancer cell lines and studied its effects on several biological processes, demonstrating that TUSC2 overexpression decreased thyroid cancer cell proliferation, migration and invasion." (PMID 31973107, 2020).
breast carcinoma (6 papers, 2018 to 2023). "Allelic loss and genetic alterations of TUSC2 are present in many cancer types, including lung and breast cancer." (PMID 37654657, 2023). "In addition to TUSC2 loss via deletion or silencing of the 3p21.3 chromosomal region, TUSC2 expression is regulated by miR-138 in breast cancer." (PMID 37173921, 2023). "TUSC2 protein expression is significantly decreased in breast cancer tissues compared to normal breast tissue." (PMID 37173921, 2023). "TUSC2P shares 89% homology with the TUSC2 3′-UTR, and TUSC2P overexpression in breast cancer cells resulted in decreased proliferation, colony formation, survival, migration, and invasion of breast cancer mediated by TUSC2." (PMID 37173921, 2023). "TUSC2P has been shown to sequester multiple miRNAs, such as miR-661, miR-229-3p, miR-93, miR-17, miR-608, and miR-502, ultimately resulting in increased TUSC2 expression in multiple breast cancer lines." (PMID 37173921, 2023). "Together, the literature establishes TUSC2 as a candidate breast cancer tumor suppressor frequently lost in breast cancer due to 3p21.3 chromosomal region deletion and silencing or via the targeting of TUSC2 mRNA by miR-138." (PMID 37173921, 2023). "For instance, pseudogene TUSC2p1 protects the expression of tumour suppressor gene TUSC2 by competitive binding with miRNA, and thus inhibits the proliferation of breast cancer cells." (PMID 30337839, 2018). "Moreover, in the case of control samples, we found overexpression of the proteins: PRDX2, PRDX5 and AIFM1 involved in ROS; TUSC2 in PMM; ALKBH7, RHOT1, SAMM50, IMMT and HSPA9 in the MMO; and FUNDC2 in MIT compared to luminal A and basal-like breast cancer tumors." (PMID 35327574, 2022).
nasopharyngeal carcinoma (6 papers, 2013 to 2023). A carcinoma arising from the nasopharyngeal epithelium. "Studies have also found that TUSC2 is downregulated in nasopharyngeal carcinoma and negatively regulates cell proliferation and cell cycle progression." (PMID 37654657, 2023). "In ovarian and nasopharyngeal cancers it has been reported that miRNA-663 promotes cell growth, migration and invasion by inhibiting TUSC2." (PMID 31973107, 2020). "All these results were consistent with the previous study, in which miR-663b promotes the proliferation, migration and invasion of nasopharyngeal carcinoma cell through targeting TUSC2." (PMID 30944041, 2019). "In malignant pleural mesothelioma and nasopharyngeal carcinoma, expression of the TUSC2 gene was found to be downregulated." (PMID 23403885, 2013). "In addition, TUSC2 is found to be down-regulated in nasopharyngeal carcinoma and negatively regulates proliferation and cell cycle progression." (PMID 30944041, 2019). "Currently, TUSC2 is down-regulated in nasopharyngeal carcinoma (NPC) genes and relates to cellular apoptosis in the chromosome deletion regions." (PMID 30944041, 2019).
esophageal squamous cell carcinoma (4 papers, 2018 to 2023). Esophageal squamous cell carcinoma (ESCC) is a type of esophageal carcinoma (EC) that can affect any part of the esophagus, but is usually located in the upper or middle third. "Moreover, the TUSC2P/miR-608/TUSC2 axis has been verified to be related to esophageal squamous cell carcinoma (ESCC)." (PMID 35387124, 2022). "TUSC2P can suppresses the tumor function of esophageal squamous cell carcinoma by regulating TUSC2 expression and may also serve as a prognostic factor for ESCC patients." (PMID 30219035, 2018).
glioblastoma (4 papers, 2014 to 2023). The most malignant astrocytic tumor (WHO grade IV). "For example, TUSC2 serves as a tumor-suppressor via up-regulating the level of miR-197 in glioblastoma." (PMID 30944041, 2019). "TUSC2 is poly-ubiquitinated on lysine residues K71, K84, and K93 in glioblastoma (GBM)." (PMID 37173921, 2023). "Over-expression of TUSC2 inhibits the growth, mobility and invasion of glioblastoma cells." (PMID 30944041, 2019). "miR-378a-5p enhances cell survival, proliferation rate and angiogenesis in glioblastoma cells, through targeting of SUFU and TUSC2." (PMID 24651706, 2014).
ovarian carcinoma (4 papers, 2019 to 2023). A malignant neoplasm originating from the surface ovarian epithelium. "Altogether, these data demonstrate that TUSC2 is down-expressed and negatively associated with miR-663 in ovarian cancer tissue." (PMID 30944041, 2019). "Furthermore, the Spearman’s correlation analysis showed that TUSC2 was negatively associated with miR-663 level in ovarian cancer." (PMID 30944041, 2019). "Finally, the expression of TUSC2 was inversely associated with the level of miR-663 in ovarian carcinoma tissue and over-expression of TUSC2 inhibited the migration and invasion abilities of SKOV3 that was promoted by miR-663." (PMID 30944041, 2019). "TUSC2 mRNA downregulation in ovarian cancer is mediated by miR-663 interaction with the TUSC2 3′-UTR." (PMID 37173921, 2023). "Consistently, up-regulation of miR-663 inhibited the mRNA and protein level of TUSC2 in ovarian carcinoma SKOV3 cell." (PMID 30944041, 2019). "Bioinformatics analysis identified TUSC2 as the directly target of miR-663 and miR-663 over-expression inhibited the level of TUSC2 in ovarian cancer cell." (PMID 30944041, 2019). "Altogether, these results indicate that miR-663 acts as a potential tumor-promoting miRNA through targeting TUSC2 in ovarian cancer." (PMID 30944041, 2019). "The levels of TUSC2 were lower in the ovarian cancer tissues in comparison with the adjacent normal tissues." (PMID 30944041, 2019). "Immunohistochemical staining analysis future proved that TUSC2 was down-regulated in ovarian cancer tissue compared to the matched normal tissue." (PMID 30944041, 2019). "Finally, we explored the level of TUSC2 in 23 pairs of ovarian carcinoma and matched normal tissues by qRT-PCR assay." (PMID 30944041, 2019). "In conclusion, miR-663 promoted ovarian cancer cell growth and progression by targeting TUSC2." (PMID 30944041, 2019). "Furthermore, we demonstrated that miR-663 facilitated ovarian cancer cell growth and progression by suppressing TUSC2." (PMID 30944041, 2019). "Finally, we found that miR-663 promoted the aggressiveness of ovarian carcinoma cellvia targeting TUSC2." (PMID 30944041, 2019). "Nevertheless, the expression of TUSC2 gene in ovarian cancer remains not well investigated." (PMID 30944041, 2019).
esophageal cancer (3 papers, 2018 to 2025). A primary or metastatic malignant neoplasm involving the esophagus. "Loss of TUSC2P and TUSC2 can lead to accelerated proliferation and invasion, decelerated apoptosis in esophageal cancer cell, suggesting TUSC2P is a bona fide tumor suppressor gene." (PMID 30219035, 2018). "In EC109 and TE-1 esophageal cancer cells, transient transfection of a pool of miRNA mimics suppressed both TUSC2 and TUSC2P mRNA abundance, as well as TUSC2 protein abundance." (PMID 30219035, 2018). "In the present study, for the first time, we reported a functional role for TUSC2P is relevant to TUSC2 biology in esophageal carcinoma as minute changes in TUSC2 can have tumorigenic consequences." (PMID 30219035, 2018). "Importantly, miR-661 stands out as a direct mediator regulating TUSC2 mRNA, confirmed through luciferase reporter assays in esophageal cancer EC109 cells." (PMID 40243558, 2025). "In further, higher level of TUSC2 and TUSC2P expression predicted better survival in esophagus cancer patients." (PMID 30219035, 2018). "Indeed, TUSC2P 3’UTR over expression resulted in a de-repression of both TUSC2 transcript and protein in EC109 and TE-1 esophageal cancer cells." (PMID 30219035, 2018).
glioma (3 papers, 2022 to 2025). A benign or malignant brain and spinal cord tumor that arises from glial cells (astrocytes, oligodendrocytes, ependymal cells). "Additionally, TUSC2 loss is studied in multiple cancers, including lung, breast, thyroid, ovarian, mesothelioma, gliomas, and other cancer types." (PMID 37173921, 2023). "Upregulation of miR-197 resulted in glioma growth inhibition, while inhibition of miR-197 attenuated TUSC2-mediated glioma tumor suppression." (PMID 37173921, 2023). "TUSC2 expression is regulated by multiple mechanisms in gliomas, including regulation via miRNA and circular RNAs, as well as regulation by post-translational modifications." (PMID 37173921, 2023). "Another miRNA, miR-106b-5p, was found to be significantly upregulated in gliomas and suppresses TUSC2 expression." (PMID 37173921, 2023). "Although TUSC2 is frequently lost in gliomas, TUSC2 overexpression in glioma cell lines has been shown to decrease cell proliferation, migration, and invasion, and increase apoptosis in vitro." (PMID 37173921, 2023). "GAS5-AS1 overexpression resulted in a significant increase in TUSC2 and promoted glioma suppression in vitro." (PMID 37173921, 2023). "Together, these studies demonstrate the importance of TUSC2 post-transcriptional regulation on promoting glioma progression." (PMID 37173921, 2023). "MiR-183-5p is significantly upregulated in glioma samples and was found to specifically target the TUSC2 3′UTR, predicted using starBase, which results in inhibition of TUSC2 mRNA translation and TUSC2-mediated glioma suppression." (PMID 37173921, 2023). "Another possible mechanism of TUSC2 mediated glioma tumor suppression may be through TUSC2 upregulation of miR-197." (PMID 37173921, 2023). "Interestingly, a tumor suppressive circular RNA, circ-EGFR, antagonizes miR-183-5p and act as a sponge to sequester miR-183-5p and ultimately inhibits glioma progression through rescuing TUSC2 expression." (PMID 37173921, 2023). "In addition to TUSC2′s normal cellular functions, TUSC2 has been studied as a tumor suppressor gene that is frequently deleted or lost in a multitude of cancers, including glioma, sarcoma, and cancers of the lung, breast, ovaries, and thyroid." (PMID 37173921, 2023). "Interestingly, miR-197 expression is significantly downregulated in gliomas and is positively upregulated upon TUSC2 protein expression." (PMID 37173921, 2023). "Overall, the current findings strongly suggest that TUSC2 is a novel glioma tumor suppressor that is frequently lost in gliomas due to miRNA-mediated downregulation and proteasomal degradation, with TUSC2 overexpression leading to glioma suppression." (PMID 37173921, 2023). "Moreover, overexpression of circ-EGFR led to increased apoptosis, decreased proliferation, migration and invasion of glioma cell lines through inhibition of miR-183-5p and ultimately the restoration of TUSC2 expression." (PMID 37173921, 2023). "Additionally, lower TUSC2 expression is predictive of worse overall survival in glioma and GBM patients." (PMID 37173921, 2023). "Through the sponge effect, lncRNA GAS5-AS1 may bind miR-106b-5p, therefore promoting the expression of its target gene TUSC2 and inhibiting the growth and spread of glioma." (PMID 36776374, 2022). "Although both circ-EGFR and TUSC2 protein expression are low in glioma samples, overexpression of circ-EGFR significantly increased TUSC2 protein expression and promoted TUSC2-mediated inhibition of glioma proliferation, migration and survival in vitro and in vivo." (PMID 37173921, 2023).
mesothelioma (3 papers, 2009 to 2023). A usually malignant and aggressive neoplasm of the mesothelium which is often associated with exposure to asbestos. "To provide insight into the pathways and genes affected by TUSC2 in MPM, we performed expression microarray profiling of mesothelioma cells transfected with TUSC2." (PMID 19852844, 2009). "The data presented here provide the first evidence that the TUSC2 protein plays an essential tumor suppressive role in asbestos-induced mesothelioma." (PMID 19852844, 2009). "TUSC2 overexpression in mesothelioma cells altered expression of 46 immune-related genes, whereas the expression of IFNγ, IFNγR, IL-1α, IL-1β, CCL5, and IL-10 was significantly increased in immune cells derived from a conventional TUSC2-KO mouse model." (PMID 37173921, 2023). "We demonstrated as well that TUSC2 expression is independent of the disease histology and stage (data not shown) suggesting that TUSC2 down-regulation may be an early event in mesothelioma development." (PMID 19852844, 2009).
metastatic tumors (3 papers, 2012 to 2023). "Although a small-scale trial with only 8 patients enrolled, this first-in-human study demonstrated that DOTAP/cholesterol liposomes can be safely administered to patients intravenously and resulted in the uptake of the TUSC2 gene by human primary and metastatic tumors as well as anti-tumor effects." (PMID 36839960, 2023). "In this study, we have shown that TUSC2 immunogene therapy combined with carboplatin and pembrolizumab results in complete tumor eradication in over 65% of humanized mice implanted with KL NSCLC metastatic tumors." (PMID 35210547, 2022).
acute myeloid leukaemia (2 papers, 2020 to 2023). "Additionally, miR-378 promotes cell survival, tumour growth and angiogenesis by targeting TUSC2 and miR-378/TUSC2 levels predict adverse prognosis in acute myeloid leukaemia patients." (PMID 31973107, 2020).
colorectal cancer (2 papers, 2025). A primary or metastatic malignant neoplasm that affects the colon or rectum. "Circ_RUSC2 increases the expression of tumor-suppressor candidate 2 (TUSC2) by sequestering miR-661, which leads to the suppression of colorectal cancer progression." (PMID 40710359, 2025).
malignant pleural mesothelioma (2 papers, 2009 to 2013). A malignant neoplasm that arises from mesothelial cells in the pleura and shows a diffuse growth pattern. "The goal of this study was to analyze possible involvement of TUSC2 in malignant pleural mesothelioma (MPM) - an aggressive inflammatory cancer associated with exposure to asbestos." (PMID 19852844, 2009).
arteritis (1 paper, 2023). An inflammatory process affecting an artery. "At two years of age, 23% of TUSC2 heterozygous KO and 20% of TUSC2 homozygous KO mice had multi-organ arteritis compared to WT mice." (PMID 37173921, 2023).